ARID1A (AT-rich interaction domain 1A)
Diseases named in the same sentence as ARID1A in open-access papers (continued):
Sharing a sentence is not in itself a finding about the gene and the disease.
ovarian carcinoma (continued). "ARID1A loss-of-function mutation accompanied by a loss of ARID1A protein expression is considered one of the most important driver events in endometriosis-associated ovarian cancer." (PMID 32868822, 2020). "Although immunohistochemical staining and assessment protocols were not unified between studies, there was an obvious difference in ARID1A protein expression between benign endometriosis and endometriosis-associated ovarian cancer." (PMID 32868822, 2020). "In particular, inactivation of ARID1A in vivo increases tumor-infiltrating lymphocytes and sensitivity to anti-PD-L1 antibody therapy in ovarian cancer, while BRCA2 mutations are enriched in melanomas responsive to ICIs." (PMID 32676589, 2020). "Recently, ovarian cancer cells carrying ARID1A mutation showed higher sensitivity to SAHA and ACY1215 treatment, through inhibition of HDAC2 and HDAC6 activity respectively." (PMID 31165775, 2019). "ROS lowers ARID1A expression by promoter methylation in ovarian cancers, and ARID1A loss sensitizes ovarian cancer cells to ROS inducing agent elesclomol." (PMID 30612957, 2019). "A targeted therapy for ARID1A-deficient tumors was developed based on data demonstrating the synthetic lethality of EZH2 inhibition in ARID1A-mutated ovarian cancer cells." (PMID 31043675, 2019). "The dependence on HDAC6 activity in ARID1A-mutated ovarian cancer cells has been reported to be correlated with direct transcriptional repression of HDAC6 by ARID1A as HDAC6 inhibition selectively promoted apoptosis of ARID1A-mutated cells." (PMID 31731647, 2019). "EHZ2 inhibition efficiently inhibits the growth of ovarian cancer cells which contain mutated ARID1A." (PMID 31426393, 2019). "The mutational status (inactivating) of ARID1A in a broad spectrum of human cancers, including ovarian cancers, established the role of ARID1A as an epigenetic tumor suppressor." (PMID 31731647, 2019). "Ovarian cancers with ARID1A mutations are particularly sensitive to epigenetic modulators, as will be discussed in detail below." (PMID 30646939, 2019). "ARID1A is highly mutated in endometriosis associated cancers such as ovarian cancer and endometrial cancer." (PMID 30356064, 2018). "Other studies have shown the essential role for histone deacetylase 8 (HDAC6) in ARID1A-mutated ovarian cancers: inhibition of HDAC6 activity in these tumors inhibited cell growth and promoted apoptosis." (PMID 29389895, 2018). "In ovarian cancer, 46% of ovarian clear-cell carcinomas and 30% endometrioid ovarian carcinomas carried ARID1A mutations." (PMID 31093468, 2018). "A previous study reported that ARID1B knockdown suppressed growth and colony formation of ARID1A-deficient ovarian cancer cell lines." (PMID 29890703, 2018). "Here, the authors demonstrate that the switch of the SWI/SNF catalytic subunits from SMARCA4 to SMARCA2 drives resistance to EZH2 inhibitors in ARID1A-mutated ovarian cancer cells." (PMID 30297712, 2018). "As dasatinib leads to synthetic lethality in ovarian clear cell tumours with an ARID1A (AT‐rich interactive domain 1A) mutation 37, our finding expands the application range of dasatinib for ovarian cancers." (PMID 29928579, 2018). "Here we show that the switch of the SWI/SNF catalytic subunits from SMARCA4 to SMARCA2 drives resistance to EZH2 inhibitors in ARID1A-mutated ovarian cancer cells." (PMID 30297712, 2018). "Among 72 and 10 such genes identified in colorectal and ovarian tumors, respectively, the most frequently mutated genes BRD4 and MLL2 (62 % of colorectal tumors) and ARID1A (50 % of ovarian carcinomas) are involved in epigenetic regulation." (PMID 29296220, 2017).
ovarian carcinoma (continued). "Although ovarian cancer cell lines with ARID1A-deficiency showed some in vitro sensitivities to PI3K/AKT inhibitors, no in vivo responsiveness of GC cells with ARID1A-deficiency effectiveness of PI3K/AKT inhibitors has been addressed." (PMID 27323812, 2016). "Examples include mutations in the ARID1A gene occurring in a subset of ovarian cancers and breast cancers along with mutations in the MLL2, MLL3, SMARCD1, NCOR1 and ARID1B genes found in a subset of breast cancers." (PMID 25468711, 2015). "AKT phosphorylation is associated with ARID1A/BAF250a deficient tumors, however in ovarian cancers the mechanism remains to be elucidated." (PMID 24559118, 2014). "A recent study has revealed frequent mutations of chromatin remodeling gene ARID1A (BAF250a) in clear cell (57%) and endometrioid (30%) types of ovarian cancers." (PMID 24213462, 2012). "Guan and colleagues recently reported that restoring wild-type ARID1A expression in ovarian cancer cells that harbor ARID1A mutations is sufficient to suppress cell proliferation and tumor growth in mice." (PMID 22481926, 2012). "It was suggested that targeting glutamate-cysteine ligase catalytic subunit (GCLC) could be an effective therapeutic strategy for ARID1A-deficient ovarian cancers." (PMID 41333220, 2025). "ERONs fall under the category of type I carcinogenic pathway of ovarian carcinomas, usually originating from benign precursor lesions, with their molecular genetic characteristics extensively studied and mutations of the ARID1A gene are most potentially associated with ERONs." (PMID 40076621, 2025). "Interestingly, ARID1A alterations seem to be associated with clinical resistance to platinum agents in ovarian cancer, as indicated by several studies." (PMID 38391958, 2024). "The functional consequences of Arid1a loss in ovarian cancer are multifaceted." (PMID 39123453, 2024). "Mutations in ARID1A have been reported in BRCA1 mutated ovarian cancer." (PMID 38940864, 2024). "Research has shown that the glutamate-cysteine ligase catalytic subunit (GCLC) could serve as a new therapeutic target for ARID1A-deficient ovarian cancer cells." (PMID 39609317, 2024). "However, ARID1A is mutated in many cancers, including ovarian cancer, endometrial cancer, gastric cancer, and bladder cancer." (PMID 38893118, 2024). "In addition, ARID1A mutations were commonly found during the early stages of endometriosis-associated ovarian carcinomas development, thus suggesting a trigger role for ARID1A loss." (PMID 36890819, 2023). "ARID1A is mutated in about 10% of all tumor types including endometrial, bladder, gastric, liver, biliopancreatic cancer, some ovarian cancer subtypes, and the extremely aggressive cancers of unknown primary." (PMID 36890819, 2023). "Moreover, an ARID1A‐deficient ovarian cancer mice model displayed an increased mutation load, elevated numbers of tumor‐infiltrating lymphocytes, and higher PD‐L1 expression levels." (PMID 37325934, 2023). "SMARCA4-mutant lung cancer cells with intact SMARCA2 depend on elevated OXPHOS activity by upregulating the master transcription factor PGC-1a38, whereas ARID1A inactivation in ovarian cancer cells causes reliance on glutamine metabolism through activating glutaminase expression." (PMID 37210563, 2023). "Nowadays, only mutations in ARID1A have been more comprehensively studied in ovarian cancer, explaining not only that their mutations cause an increase in MYC expression and affect tumour progression, but also that therapies targeting ARID1A mutations have emerged in the clinic." (PMID 36883311, 2023). "The same group showed earlier that HDAC6 activity is essential in ARID1A-mutated ovarian cancers." (PMID 36980292, 2023).
ovarian carcinoma (continued). "Moreover, EZH2 inhibitor GSK126 can lead to the decline of ovarian cancer carrying ARID1A mutation in vivo." (PMID 38008753, 2023). "This raises the question regarding the significance of mutations in the ARID1A gene as an earlier biomarker in endometriosis patients to tackle ovarian cancer initiation, as partial loss of BAF250a expression has been found in lesions of patients with endometriosis." (PMID 38029403, 2023). "Interestingly, inactivation of SWI/SNF complex by ARID1A mutation has been reported to be associated with the decreased cell death in ovarian cancer cells." (PMID 35069887, 2022). "In analyzing the correlations between mutations or other aberrations in ARID1A and BAF250a expression in ovarian cancer and contiguous AE, eight studies detected possible correlations, with a rate of ARID1A mutations and BAF250A loss of expression in AE ranging from 23.8 to 100%." (PMID 35457244, 2022). "This interaction would suggest that targeting TAMs could be relevant in synergising immune checkpoint‐based immunotherapy in various tumour types, and in the context of endometriosis‐related ovarian cancers, specifically ARID1A‐mutated tumours." (PMID 35647895, 2022). "ARID1A mutations are also common in endometriosis-associated ovarian cancers." (PMID 36153585, 2022). "ARID1A mutations are frequently observed in endometriosis-associated ovarian cancers." (PMID 36153585, 2022). "Indeed, ovarian cancer, the most dominant in our rare malignancy population (19%), accounted for 52% of all ARID1A-mutated cases; however, is found at lower frequency in the other populations." (PMID 36088851, 2022). "Similarly, inhibition of the EZH2 methyltransferase subunit of the PRC2 complex in ARID1A-mutated ovarian cancer cells also results in a SL interaction related to PI3 kinase-AKT signaling." (PMID 36605718, 2022). "The frequency of ARID1A variations in ovarian clear cell carcinomas is up to 60% in the US, Canada, and Japan, indicating that ARID1A deficiency may be a potential biomarker for precision medicine of ovarian cancer." (PMID 35421925, 2022). "For example, in ovarian cancer, only the simultaneous truncation mutation and missense mutation of ARID1A and PI3KCA may cause the growth of malignant metastatic tumor cells." (PMID 34799997, 2022). "In the case of endometrial and ovarian cancers, these mutations might either hamper the nuclear import of ARID1A, or affect the ability of ARID1A to interact with the subunits of SWI/SNF complex." (PMID 33748136, 2021). "Recent work in ovarian cancer demonstrated that mutations in ARID1A confer sensitivity to HDACi." (PMID 34257602, 2021). "This is supported by additional studies of cancer cell lines that showed that partial depletion of ARID1A enhanced cell proliferation and restoring expression of ARID1A in both ARID1A-deficient breast cancer cell lines and mouse ovarian cancer models was sufficient to inhibit cell proliferation." (PMID 32629987, 2020). "Immunohistochemical analyses of ARID1A in ovarian cancer demonstrated that 0–40% of endometriosis lesions adjacent to ovarian cancer showed a loss of ARID1A protein expression, whereas all distant endometriosis lesions in ovarian cancer expressed ARID1A7,17,19,21,33." (PMID 32868822, 2020). "Based on these pieces of evidence, the mutation of ARID1A and/or the loss of expression of BAF250a may appear as a promising strategy for molecular diagnosis of endometriosis-associated ovarian cancer." (PMID 31717614, 2019). "In addition, ARID1A cooperates with other mutated epigenetic or oncogenic signaling such as mutated PI3KCA in ovarian cancer." (PMID 31426393, 2019).
ovarian carcinoma (continued). "The mutation of ARID1A has been most prevalent in cancers of ovary and endometrium." (PMID 31731647, 2019). "Thus pharmacological inhibition of EZH2 represents a novel treatment strategy for ovarian cancers involving ARID1A mutations." (PMID 30064416, 2018). "Studies examining endometriotic lesions and ovarian cancer from the same patient have shown concordant mutations in ARID1A, phosphatase and tensin homolog (PTEN), PIK3CA, and KRAS, suggesting that mutations in endometriosis cause a predisposition to ovarian cancer." (PMID 30087267, 2018). "Functional studies of ovarian cancer cell lines reveal numerous gene targets of the SWI/SNF complex which may be impacted by ARID1A mutation, including cyclins, c-myc, and the Polycomb complexes." (PMID 29093822, 2017). "After 2008, annual research productivity increased to more than 1000 papers when new hypotheses regarding the origin of high-grade serous subtypes and the association of ovarian cancers with ARID1A mutations and endometriosis were proposed." (PMID 28086974, 2017). "In an Apc- and Pten-defective mouse ovarian cancer model loss of ARID1A enhances epithelial differentiation and prolongs survival, which may account for the better prognosis of ovarian cancer arising in endometriosis." (PMID 27992377, 2017). "However, it is widely discussed at which stage of ovarian cancer development ARID1A mutations occur." (PMID 26413541, 2015). "Several studies have related ARID1A to transcriptional regulation, particularly nuclear hormone-induced transcription and expression of cell-cycle regulators; mutations of ARID1A are frequently seen in hormone-responsive cancers, like breast and ovary cancers." (PMID 26384299, 2015). "There is a paucity of information regarding the mechanisms through which ARID1A loss-of-function acts in cancer cells and there are conflicting reports regarding the effects of its inactivation: in ovarian cancer, a moderate knockdown was associated with increased proliferation." (PMID 23650517, 2013). "We took note that a number of cell lines often used as high-grade serous models or generically as “ovarian carcinoma” had both ARID1A mutations and immuno-profiles consistent with the endometrioid type, the third most common type accounting for less than 10% of ovarian carcinomas." (PMID 24023729, 2013). "Similarly, the phosphatidylinositol 3-kinase/protein kinase B/mammalian target of rapamycin pathway, which is related to the ARID1A pathway, may be abnormally activated in endometriosis-associated ovarian cancer." (PMID 41303820, 2025). "Similarly, ARID1A loss in ovarian cancer upregulates glutaminase 1, driving glutamine utilization." (PMID 41323791, 2025). "Finally, ARID1A mutations were also found in atypical endometriosis adjacent to tumors but not in distant endometriotic lesions, indicating involvement in the early transformation of endometriosis into ovarian cancer." (PMID 40364006, 2025). "ARID1A mutations are found in approximately 10% of all cancer types, including those of the endometrium, bladder, stomach, liver, pancreatobiliary system, some ovarian cancer subtypes, and cancer of unknown primary origin." (PMID 41465243, 2025). "Similarly, targeting EZH2 in Arid1a-mutated ovarian cancer cells shows synergistic sensitivity." (PMID 39123453, 2024). "Thus, ARID1A-deficient ovarian cancers may be susceptible to drugs targeting GCLC since their efficiency is enhanced by a low SLC7A11 expression that keeps GSH content at low levels." (PMID 38203758, 2024). "Notably, ARID1A mutation exists in the preneoplastic lesions, which occurs in the early stage of transformation from endometriosis into endometriosis-associated ovarian cancers, which may be helpful to the early diagnosis of endometrial cancer." (PMID 34671561, 2021).
ovarian carcinoma (continued). "In addition to PDAC, ARID1A is also frequently mutated in other cancer types, with 45.2% mutation rate in ovarian cancer, 18.7% in gastric cancer, 18.6% in bladder cancer, 13.7% in hepatocellular cancer, 11.5% in melanoma, 9.4% in colorectal cancer, 8.2% in lung cancer, and 2.5% in breast cancer." (PMID 33983114, 2021). "To further establish that ARID1A is responsible for increases in mitochondrial respiration, we conducted complementary experiments and tested whether ectopic expression of ARID1A in the ARID1A-mutated TOV-21G ovarian cancer cell line would result in decreases in mitochondrial activity." (PMID 33947138, 2021). "Thus, ARID1A deficiency has potential as a biomarker for precision medicine of ovarian cancer." (PMID 33917230, 2021). "ARID1A deficiency is related to a mismatch repair-deficient phenotype with ARID1A mutant tumours showing an increase in TILs, activation of the immune checkpoint and sensitization to the PD-L1 checkpoint blockade in ovarian cancer in in vivo mouse models compared to ARID1A wild-type tumours." (PMID 34359755, 2021). "In vivo study also shows that ARID1A deficiency could promote tumor formation in ovary cancer." (PMID 26569409, 2015). "BAF is mutated in 20% of human cancers and major components of this enzyme complex like ARID1A and SMARCA2/4 are consistently mutated in specific histologies of ovarian cancer." (PMID 41301911, 2025). "In a functional characterization paper, the authors investigated the effects of overexpressing and knocking down ARID1A in ovarian cancer cell lines and xenograft models." (PMID 40429787, 2025). "We discuss personalized clinical strategies, including risk-based surveillance for patients with atypical lesions or ARID1A alterations, and implications for ovarian cancer management in endometriosis." (PMID 41465243, 2025). "Taken together, our novel selective HDAC6 inhibitor 25253 demonstrated a synergic effect when combined with Taxol not only in ARID1A-null TOV21G cells but also in ARID1A wild-type ES-2 ovarian cancer cells." (PMID 40649308, 2025). "Loss of EZH-2 antagonists such as ARID1A and SMARCA2/4 leads to the repression of tumor suppressor genes in ovarian cancer." (PMID 41301911, 2025). "Exome sequencing revealed that 79% of lesions (EC and/or DIE) carried mutations, with 26% involving ARID1A, PIK3CA, KRAS, or PPP2R1A, among which PIK3CA and KRAS are frequently altered in ovarian cancer." (PMID 41465243, 2025). "Genetic mutations, most notably in the ARID1A gene, are involved in the pathogenesis of EAOC (endometriosis-associated ovarian cancer); these disrupt chromatin remodeling and activate oncogenic pathways such as PI3K/Akt." (PMID 40364006, 2025). "ARID1A overexpression resulted in a more differentiated ovarian cancer cell line and upon knockdown, the same cancer cell lines started expressing cancer stem cell markers: NANOG, OCT3/4, and SOX2." (PMID 40429787, 2025). "Some studies have reported that HDAC6 inhibitors can enhance the activity of Taxol in ARID1A-null ovarian cancer cells and tumor models, partly due to the disruption of microtubule dynamics." (PMID 40649308, 2025). "In several breast and ovarian cancer cell lines, ARID1A deletion resulted in resistance to PARP inhibitory therapy." (PMID 39697230, 2024). "This histological profile would normally be suggestive of Type I ovarian cancer and the reported mutations of PTEN, PIK3CA and ARID1A genes are consistent with this." (PMID 38940864, 2024).